PRKACB (protein kinase cAMP-activated catalytic subunit beta)
Description:
Mediates cAMP-dependent signaling triggered by receptor binding to GPCRs. PKA activation regulates diverse cellular processes such as cell proliferation, the cell cycle, differentiation and regulation of microtubule dynamics, chromatin condensation and decondensation, nuclear envelope disassembly and reassembly, as well as regulation of intracellular transport mechanisms and ion flux. Regulates the abundance of compartmentalized pools of its regulatory subunits through phosphorylation of PJA2 which binds and ubiquitinates these subunits, leading to their subsequent proteolysis. Phosphorylates GPKOW which regulates its ability to bind RNA. Acts as a negative regulator of mTORC1 by mediating phosphorylation of RPTOR.
Synonyms: PKA C-beta; PKACb; CAFD2
Tractability: Small molecule: a drug acting on it is in phase 1 trials; a high-quality ligand is known; it belongs to a druggable protein family. Antibody: UniProt places it where antibodies can reach, with high confidence; its Gene Ontology location is reachable by antibodies, with medium confidence. PROTAC: ubiquitination databases record sites on it; its protein half-life has been measured; a small molecule that binds it is known.
Target class: Kinase; AGC protein kinase PKA family; Protein Kinase; AGC protein kinase group; Enzyme
Gene: Protein-coding gene on chromosome 1 (84,078,062 to 84,238,498, forward strand). Ensembl gene ENSG00000142875.
Subcellular location: Cytoplasm; Cell membrane; Membrane; Nucleus
Subcellular location (Human Protein Atlas): Cytosol; Basal body; Cytokinetic bridge; Microtubules; Primary cilium
Pathways (Reactome):
Signal Transduction: DARPP-32 events; Degradation of GLI1 by the proteasome; Degradation of GLI2 by the proteasome; GLI3 is processed to GLI3R by the proteasome; GPER1 signaling; Hedgehog 'off' state; MAPK6/MAPK4 signaling; PKA activation; PKA-mediated phosphorylation of CREB; VEGFA-VEGFR2 Pathway
Metabolism: Glucagon-like Peptide-1 (GLP1) regulates insulin secretion; PKA activation in glucagon signalling; PKA-mediated phosphorylation of key metabolic factors; Regulation of glycolysis by fructose 2,6-bisphosphate metabolism; Regulation of insulin secretion; Triglyceride catabolism
Developmental Biology: RET signaling; ROBO receptors bind AKAP5
Disease: ADORA2B mediated anti-inflammatory cytokines production; FCGR3A-mediated IL10 synthesis
Immune System: CD209 (DC-SIGN) signaling; Rap1 signalling
Transport of small molecules: HDL assembly; Vasopressin regulates renal water homeostasis via Aquaporins
Cellular responses to stimuli: High laminar flow shear stress activates signaling by PIEZO1 and PECAM1:CDH5:KDR in endothelial cells
Hemostasis: Factors involved in megakaryocyte development and platelet production
Neuronal System: CREB1 phosphorylation through the activation of Adenylate Cyclase
Gene Ontology:
Molecular function: ATP binding; cAMP-dependent protein kinase activity; magnesium ion binding; potassium channel inhibitor activity; protein binding; protein serine kinase activity; protein serine/threonine kinase activity; protein kinase activity
Biological process: negative regulation of TORC1 signaling; protein phosphorylation; adenylate cyclase-activating G protein-coupled receptor signaling pathway; adenylate cyclase-modulating G protein-coupled receptor signaling pathway; high-density lipoprotein particle assembly; positive regulation of insulin secretion; renal water homeostasis; signal transduction; vascular endothelial cell response to laminar fluid shear stress
Cellular component: centrosome; cytoplasm; cytosol; extracellular exosome; plasma membrane; cAMP-dependent protein kinase complex; ciliary base; nucleoplasm; nucleus; membrane
Genetic constraint (gnomAD): Loss-of-function variants: 12 observed, 37.92 expected, observed/expected ratio (o/e) 0.32, 90% interval 0.2 to 0.51. The upper end of that interval is the gene's LOEUF score, 0.51, which puts it in group 2 of 6, group 1 being the genes least tolerant of losing a copy. Missense variants: 258 observed, 382.49 expected, observed/expected ratio (o/e) 0.67, 90% interval 0.61 to 0.75. Synonymous variants: 123 observed, 130.07 expected, observed/expected ratio (o/e) 0.95, 90% interval 0.82 to 1.1.
Homologues: Orthologues: chimpanzee PRKACB (100% identical), macaque PRKACB (99% identical), rabbit PRKACB (99% identical), dog PRKACB (97% identical), guinea pig PRKACB (96% identical), rat Prkacb (93% identical), pig PRKACB (89% identical), mouse Prkacb (83% identical), zebrafish prkacba (80% identical), tropical clawed frog prkaca (79% identical), zebrafish prkacab (77% identical), Drosophila melanogaster CG12069 (39% identical), and 3 more. Paralogues in human: PRKACA (80% identical), PRKACG (68% identical), PRKX (43% identical), PRKG1 (39% identical), PRKG2 (38% identical).
Diseases named in the same sentence as PRKACB in open-access papers:
PRKACB is named in the same sentence as 71 diseases in open-access papers, as found by Europe PMC text mining. Sharing a sentence is not in itself a finding about the gene and the disease. The quoted sentences say what the papers report.
liver cancer (11 papers, 2014 to 2024). An epithelial or non-epithelial malignant neoplasm that arises from the liver. "first elucidated the mechanism of lncRNA-related ceRNAs in liver cancer and the role of LncRNA HULC/miR-372/PRKACB axis in liver cancer." (PMID 38309281, 2023). "The lncRNA highly upregulated in liver cancer (HULC) was found to inhibit miR-372 as a ceRNA in liver cancer, thereby increasing the expression of cAMP-dependent protein kinase catalytic subunit beta (PRKACB)." (PMID 34760707, 2021). "Unfortunately, we are yet to conduct experimental studies exploring the potential carcinogenic mechanism of PRKACB in the development of liver cancer." (PMID 32626531, 2020). "HULC (highly upregulated in liver cancer) is known to reduce the expression of protein kinase cAMP-activated catalytic subunit beta (PRKACB) and to increase the HMGA2 oncogene via interaction with miR-372 and miR-186 in HCC." (PMID 32937886, 2020). "HULC diminishes the expression and activity of miR-372 and sequesters miR-372 from its target gene protein kinase cAMP activated catalytic subunit beta (PRKACB) in liver cancer cells." (PMID 31480503, 2019). "HULC, which is significantly upregulated in hepatocellular carcinoma, can reduce the expression and activity of miR-372 in liver cancer, which derepresses the translation of its target gene PRKACB and induces phosphorylation of the cAMP response element binding protein in liver cancer." (PMID 32256525, 2020). "In the iCCA vs. CIR comparison, seven proteins showed higher abundance in the iCCA patient group, among which haptoglobin (HP), cAMP-dependent protein kinase catalytic subunit beta (PRKACB), heat shock protein (HSP) 90-alpha A2 (HSP90AA2P) were previously reported with respect to liver cancer." (PMID 39286634, 2024). "Highly up-regulated liver cancer (HULC) may act as an endogenous ‘sponge’, which down-regulates miR-372 leading to reducing translational repression of its target gene, PRKACB." (PMID 25057983, 2014).
hepatocellular carcinoma (8 papers, 2015 to 2025). A malignant tumor that arises from hepatocytes. "The lncRNA HULC is highly upregulated in hepatocellular carcinoma and has multiple binding sites with miR-372, which results in reduced translation of the target gene PRKACB." (PMID 34235197, 2021). "HULC lncRNA also acts as ceRNA of the protein coding gene PRKACB that induces activation of CREB to modulate self-regulation in hepatocellular carcinoma." (PMID 26253106, 2015). "Moreover, it was recently found that miR-302a-3p suppresses hepatocellular carcinoma progression by targeting the 3′-UTR of PRKACB gene." (PMID 31998791, 2020). "For example, HULC is an lncRNA that is specifically overexpressed in hepatocellular carcinoma (HCC) and functions as a miRNA sponge to restrain the activity of many miRNAs, such as hsa-miR-372-5p, leading to the suppression of its target gene PRKACB." (PMID 28164117, 2017). "In hepatocellular carcinoma, the binding of HULC to miR-372 attenuates miRNA-mediated translation inhibition of PRKACB and induces the phosphorylation of CREB." (PMID 34375306, 2021). "In hepatocellular carcinoma, LncRNA HULC directly binding to miR-372 to regulate its expression and the activity of PRKACB." (PMID 31308265, 2019).
breast carcinoma (7 papers, 2014 to 2023). "In gynecological and breast cancers, we found overexpressed PRKACB in BRCA (22%, FDR = 3.7E − 5), MST1 in UCEC (21%, FDR = 1E − 4), and CALM1 in OV (19%, FDR = 1.3E − 3)." (PMID 34552204, 2021). "Some researches declared that PRKACB mutations could cause adrenal and bile duct tumors 12,13, and that high expressions of PRKACB is related to drug resistance in patients diagnosed with breast cancer." (PMID 32626531, 2020).
colorectal cancer (6 papers, 2017 to 2025). A primary or metastatic malignant neoplasm that affects the colon or rectum. "For instance, Lower PRKACB expression was found in tumor tissues and significantly associated with unfavorable overall survival in patients with colorectal carcinoma." (PMID 37293295, 2023). "The expression of PRKACB was downregulated in both colorectal cancer and non-small cell lung cancer (NSCLC)." (PMID 40302936, 2025). "Consequently, we can confirm that PRKACB plays an important role in patients with colorectal cancer and affects the prognosis of patients." (PMID 32626531, 2020). "However, the prognostic value of PRKACB expression in colorectal cancer (CRC) patients remains controversial." (PMID 32626531, 2020). "Nonetheless, the exact role played by PRKACB in colorectal cancer is still unknown." (PMID 32626531, 2020). "To further check the role of PRKACB, MECOM, PLA2G4C, FGF2 and FGF in colorectal cancer, we further analyzed the genes involved in the MAPK pathway for their association with patient’s survival using the survExpress online tool." (PMID 28749961, 2017).
non-small cell lung carcinoma (5 papers, 2013 to 2025). A group of at least three distinct histological types of lung cancer, including non-small cell squamous cell carcinoma, adenocarcinoma, and large cell carcinoma. "PRKACB mutations and gene fusion of PRKACB can lead to adrenal, bile duct, liver, and pancreatic cancers 12,13, meanwhile down-regulation of PRKACB expression may be associated with poor survival in patients with non-small cell lung cancer." (PMID 32626531, 2020). "The PRKACB mRNA and protein levels were decreased in non-small cell lung cancer and exogenous PRKACB impaired the proliferative and invasive ability of LTEP-A2 cells." (PMID 37124518, 2023). "Conversely, another study suggested that the PRKACB might act as a tumor suppressor gene in non-small cell lung cancers." (PMID 32626531, 2020). "There is a negative correlation between PRKACB levels and cell growth in non-small cell lung cancer tissue and transfection of PRKACB into LTEP-A2 cells decreased cell proliferation." (PMID 39342354, 2024).
leukemia (4 papers, 2017 to 2023). A malignant (clonal) hematologic disorder, involving hematopoietic stem cells and characterized by the presence of primitive or atypical myeloid or lymphoid cells in the bone marrow and the blood. "Current studies have found the likely tumorigenic roles of PRKACB in diverse malignant tumors, including gastrointestinal cancer (gastric, colon and pancreatic tumors) and others (breast, ovary, leukemia and brain tumors)." (PMID 31285693, 2019). "MiR-496 antagonized the proliferative and anti-apoptotic effects of PRKACB on leukemia cells." (PMID 37124518, 2023). "Therefore, our finding that hematopoietic transcription factors, such as TAL1 and RUNX1, influence expression of PRKACB isoforms could connect aberrant transcription factor function with altered PKA signalling in leukemia." (PMID 29069738, 2017). "Our observations open the possibility of a regulatory loop between transcriptional regulation of PRKACB isoform expression and the modification status of TAL1 in differentiation and leukemia." (PMID 29069738, 2017). "Through dual-luciferase reporter and probe assays, miR-496 and its target gene, protein kinase cAMP-dependent catalytic β (PRKACB), were found to be regulated by circRNA-DLEU2, providing mechanistic insight into the role of this circRNA in leukemia biogenesis and progression." (PMID 37124518, 2023).
melanoma (4 papers, 2023 to 2025). A malignant, usually aggressive tumor composed of atypical, neoplastic melanocytes. "The circANKRD52 promoted the growth and invasion of melanoma cells by sponging miR‐141‐3p and upregulating PRKACB." (PMID 41173801, 2025). "PRKACB was selected as a functionally relevant target of miR‐141‐3p based on its Database‐predicted high expression in melanoma tissues and complete experimental validation by luciferase." (PMID 41173801, 2025). "The increased expression of PRKACB in melanoma tissues was determined by RT‐qPCR, and PRKACB possessed an inverse correlation with miR‐141‐3p expression but a positive correlation with circANKRD52 expression." (PMID 41173801, 2025). "Our findings demonstrate that circANKRD52 promotes the growth and angiogenesis of melanoma cells by sponging miR‐141‐3p and upregulating PRKACB." (PMID 41173801, 2025). "Herein, we found circANKRD52 could bind to miR‐141‐3p, leading to upregulation of PRKACB, and downregulation of miR‐141‐3p restored melanoma cell growth, invasion, and angiogenic capabilities of HUVECs." (PMID 41173801, 2025). "The circANKRD52 promoted the growth and invasion of melanoma cells by sponging miR‐141‐3p and upregulating PRKACB, and might provide a potential biomarker for treatment of melanoma." (PMID 41173801, 2025). "In our study, the positive correlation between PRKACB expression and immune score, suggests that PRKACB may facilitate anti-tumor immunity in melanoma." (PMID 39835132, 2024). "Moreover, circANKRD52 could bind to miR‐141‐3p, leading to upregulation of PRKACB, and downregulation of miR‐141‐3p restored melanoma cell growth and invasion." (PMID 41173801, 2025). "Moreover, PRKACB blocks T‐cell chemokines to help melanoma escape immunity." (PMID 41173801, 2025). "In contrast, our study developed a gene-based prognostic model to predict NK cell activation and melanoma prognosis, identifying CCNB1, PRKACB, FCGR2C, and CCL8 as key prognostic genes." (PMID 40430484, 2025). "The upregulation of AHR, MAP2K1, and PRKACB, alongside the downregulation of KLF5 and PIK3R2, suggests that these genes play critical roles in melanoma progression through various signaling pathways." (PMID 39835132, 2024). "This study presents a comprehensive analysis of AhR-related genes in melanoma, highlighting MAP2K1, PRKACB, KLF5, and PIK3R2 as key prognostic markers and potential therapeutic targets." (PMID 39835132, 2024). "These analyses aim to uncover potential therapeutic strategies for melanoma by targeting key molecules in the AHR, MAP2K1, KLF5, PRKACB, and PIK3R2 signaling pathways." (PMID 39835132, 2024). "This study provides an integrated approach to understanding the AhR pathway’s role in melanoma, identifying MAP2K1, PRKACB, KLF5, and PIK3R2 as critical prognostic markers and therapeutic targets." (PMID 39835132, 2024). "These analyses aim to identify therapeutic strategies for melanoma by targeting key genes (AHR, MAP2K1, KLF5, PRKACB, PIK3R2) and their regulatory RNA networks, offering potential for personalized treatments and novel biomarkers to improve clinical outcomes." (PMID 39835132, 2024). "Our analysis identified a robust prognostic model, with four AhR-related genes (MAP2K1, PRKACB, KLF5, and PIK3R2) emerging as key contributors to melanoma progression." (PMID 39835132, 2024). "An examination of the expression profiles of melanoma patients from the TCGA database, compared to normal controls from the GTEx database, revealed that AHR, MAP2K1, and PRKACB were upregulated in melanoma, whereas KLF5 and PIK3R2 were downregulated." (PMID 39835132, 2024).
pancreatic cancers (4 papers, 2019 to 2025). "Recently, the presence of the PRKACA and PRKACB fusion genes has been detected in various cancers such as bile duct cancers, fibrolamellar hepatocellular carcinoma, and pancreatic cancers, and there is a possibility that this might be implicated in the pathogenesis of cancer 9-11." (PMID 32626531, 2020). "For instance, abnormal expression of PRKACB can suppress the PKA/CREB pathway, promoting tau hyperphosphorylation and brain aging, and is associated with colorectal and pancreatic cancers." (PMID 41257548, 2025). "Alterations to PRKACB function through gene fusion are mutually exclusive from GNAS mutation in biliary tract cancer and either mutually exclusive in pancreatic cancer or not completely mutually exclusive." (PMID 39342354, 2024).
Cushing syndrome (3 papers, 2022 to 2025). Cushing's syndrome (CS) encompasses a group of hormonal disorders caused by prolonged and high exposure levels to glucocorticoids that can be of either endogenous (adrenal cortex production) or exogenous (iatrogenic) origin. "Additionally, one PKAcβ (encoded by PRKACB) mutation, S53L, has been identified as a driver of Cushing’s syndrome." (PMID 41511347, 2025). "Mutations in PRKACA (the PRKACB paralogue) and GNAS are mutually exclusive in Cushing’s syndrome and result in similarly sized adrenocortical adenoma diameter and similar increases in serum cortisol." (PMID 39342354, 2024).